NECTIN4 (nectin cell adhesion molecule 4)
Diseases named in the same sentence as NECTIN4 in open-access papers (continued):
Sharing a sentence is not in itself a finding about the gene and the disease.
bladder cancer (continued). "EV is associated with increased PD-L1 expression, along with upregulation of NF-κB and STAT3, suggesting a mechanistic link that may contribute to immune modulation in nectin-4-high bladder cancer cells." (PMID 40999385, 2025). "This study provides the first evidence that EV is associated with increased PD-L1 expression, along with upregulation of NF-κB and STAT3, suggesting a mechanistic link that may contribute to immune modulation in nectin-4-high bladder cancer cells." (PMID 40999385, 2025). "Therefore, the proposed approach of combining Nectin-4-MMAE with autophagy inhibitors presents a promising avenue for bladder cancer treatment, underpinned by robust experimental validation and theoretical rationale." (PMID 38664366, 2024). "A previous immunohistochemical study showed a wide expression of Nectin-4 in different solid carcinomas ranging from Nectin-4 positivity in 55% of esophageal to 83% of bladder cancer with a moderate or high expression ranging from 18% in ovarian cancer to 60% in bladder cancer." (PMID 37480387, 2023). "Notably, in bladder cancer, the discovery of new targets paved the way to various clinical trials that explored the use of ADCs directed against Nectin-4, Trop-2, or HER-2 with significant clinical benefits in terms of overall response and survival." (PMID 37763107, 2023). "Nectin-4 has been shown to be a successful therapy target in solid tumors including bladder cancer." (PMID 36268557, 2022). "In a previous study, it has been found that Nectin-4 mRNA, a poliovirus receptor-related protein-4 (PVRL4), is highly expressed in cancer cells, especially in bladder cancer (BC) and that such aberrant expression is associated with cancer progression and poor prognosis." (PMID 35953604, 2022). "NECTIN4 is a type I transmembrane protein that is found overexpressed (in comparison to the respective normal tissue) at the cell surface of several human epithelial malignancies, including cancers of the urinary bladder, breast and lung." (PMID 35484425, 2022). "Thus, Nectin-4 is an attractive target due to its preferential overexpression in bladder cancer relative to normal tissues." (PMID 33019653, 2020). "In urothelial carcinoma, Nectin-4 expression were detected in 434 (82.8%) of 524 bladder cancers (1+, 118 [22.5%]; 2+, 154 [29.4%]; and 3+,162 [30.9%]), and another study reported that Nectin-4 expression level (median H-score) was 290(range:14–300) in 125 UCs including 44 UTUCs (35%)." (PMID 32751328, 2020). "While this may reflect the known lower expression of nectin-4 in basal-type bladder cancer cell lines such as T24 compared to luminal-type lines like RT4, as reported in previous studies, the absence of a dedicated positive control and optimization steps limits the strength of this result." (PMID 40999385, 2025). "However, these Nectin-4 expression data of urothelial carcinoma were investigated predominantly in bladder cancer, and the expression status in UTUC remains unclear." (PMID 32751328, 2020). "A case report of a patient with bladder cancer whose disease had progressed after treatment with enfortumab vedotin, an ADC which targets nectin-4, reported high levels of P-gp in the resistant tumor." (PMID 40501953, 2025). "Taken together, these data demonstrate that TM4SF1 may be a new therapeutic target for TM4SF1-expressing bladder cancers, including tumors with variant histology and those lacking NECTIN4 expression, and can be successfully targeted using CAR T cell therapy in a mouse xenograft model." (PMID 40527915, 2025). "The distribution of the top 5 molecular targets in the global ADC clinical trials in bladder cancer showed that HER2, NECTIN4, immune checkpoints (PD-1), TROP2 and epidermal growth factor receptor (EGFR) were the most widely studied targets." (PMID 40433388, 2025).
bladder cancer (continued). "Our results reveal that inhibiting autophagy strengthens the antitumor effects of Nectin-4-MMAE, underscoring the potential of a combined therapeutic approach utilizing Nectin-4-MMAE and autophagy inhibitors for more effective bladder cancer treatment." (PMID 38664366, 2024). "In our study, we introduce a novel therapeutic approach by proposing the combination of Nectin-4-MMAE and autophagy inhibitors for bladder cancer treatment." (PMID 38664366, 2024). "Enfortumab verdotin (EV), a Nectin-4-targeted antibody conjugated with the microtubule disrupting agent monomethyl auristatin E (MMAE), has demonstrated excellent response rates in locally advanced bladder cancer." (PMID 36268557, 2022). "As our study confirmed strong expression values of Nectin-4 and Trop-2, antibody-drug conjugate therapies should also be considered for nonurothelial subtypes of bladder cancer." (PMID 34768978, 2021). "Interestingly, nectin-4 accumulates in the cytoplasm within squamous differentiation or plasmacytoid subtype in bladder cancer, especially within metastatic specimens, but not neuroendocrine differentiation." (PMID 38392058, 2024). "Nectin-4 negative bladder cancer cells 5637 and T24 were designated as negative controls." (PMID 38664366, 2024). "Early preclinical work in RT112 bladder cancer cell lines suggests that resistance to EV is mainly mediated by resistance to the MMAE payload and seems to be independent of the expression of surface target Nectin-4." (PMID 38540132, 2024). "In addition, the absence of elevated markers of urothelial carcinoma such as NECTIN4 and GATA3 in the present case suggests that the malignancy is unlikely to be derived from bladder cancer." (PMID 37240308, 2023).
urothelial carcinoma (51 papers, 2020 to 2026). A malignant neoplasm derived from the transitional epithelium of the urinary tract (urinary bladder, ureter, urethra, or renal pelvis). "Greater Nectin-4 expression, however, has been reported in aggressive urothelial carcinoma tissue variants, suggesting potential prognostic relevance." (PMID 41590351, 2026). "Recently, enfortumab vedotin, targeting cancer-associated NECTIN4, has been approved for the treatment of advanced urothelial carcinoma." (PMID 35484425, 2022). "Notably, the plasmacytoid variant of urothelial carcinoma has been shown to have some of the highest expression of nectin-4 with 88.9% of PUC samples staining positive in one study." (PMID 40989700, 2025). "Nectin-4 expression levels have been associated with different subtypes of urothelial carcinoma." (PMID 38606099, 2024). "Nectin‐4 expression varies across molecular subtypes of urothelial carcinoma, with higher expression in luminal subtypes than in basal subtypes." (PMID 41403786, 2026). "To assess the binding specificity of [68Ga]AJ647 to Nectin-4, we selected several urothelial carcinoma (UC) cell lines, including T24 (low Nectin-4, control cell line), SCaBER, RT112, UC9, UC14, and HT1376 (high Nectin-4)." (PMID 41499516, 2026). "Enfortumab vedotin (EV), a Nectin‐4–targeted antibody–drug conjugate, is active in previously treated urothelial carcinoma." (PMID 41472900, 2026). "Nectin‐4 is frequently expressed in urothelial carcinoma and is utilized as the therapeutic target of EV." (PMID 41403786, 2026). "For example, Enfortumab Vedotin is an ADC targeting Nectin-4, which is currently only approved for treating advanced urothelial carcinoma." (PMID 40046734, 2025). "Two available MIBC studies on this topic reported similar Nectin‐4 positivity rates of 80% (57/82) and 68% (15/22) in pure urothelial carcinoma NOS, when compared with our cohort, which showed a rate of 70% (95/136)." (PMID 39801278, 2025). "[68Ga]N188 PET targeting Nectin-4 has shown high accumulation in lesions, correlating with Nectin-4 expression levels as confirmed by immunohistochemistry in patients with advanced urothelial carcinoma." (PMID 40717183, 2025). "Enfortumab vedotin—an antibody-drug conjugate targeting nectin-4— is used in the treatment of patients with urothelial carcinoma." (PMID 41303221, 2025). "MPUCs exhibited the highest Nectin‐4 expression level, with a positivity rate of 83% compared to 70% in pure urothelial carcinoma NOS." (PMID 39801278, 2025). "The first study also included SARC urothelial carcinoma samples and described a Nectin‐4 positivity rate of only 10% (1/10), which is similar to that found in our study – positive expression was observed in only 2/12 tumours." (PMID 39801278, 2025). "Enfortumab vedotin (EV), a Food and Drug Administration–approved antibody–drug conjugate targeting nectin-4, has shown promise in treating urothelial carcinoma." (PMID 40774696, 2025). "Many histological subtypes showed Nectin‐4 expression levels similar to those found in pure urothelial carcinoma NOS, while the Sq urothelial carcinomas and the SARC subtype exhibited significantly lower Nectin‐4 levels." (PMID 39801278, 2025). "Enfortumab vedotin (EV), an antibody–drug conjugate targeting Nectin-4, has demonstrated efficacy against advanced urothelial carcinoma." (PMID 40496844, 2025). "NECTIN4-directed CAR-T cells demonstrated potent cytotoxicity across urothelial carcinoma cells expressing varying levels of endogenous NECTIN4, including those resistant to enfortumab vedotin." (PMID 41425090, 2025). "Nectin-4, already validated as a therapeutic target through the antibody–drug conjugate enfortumab vedotin, approved for advanced urothelial carcinoma has further spurred the development of NECTIN4-directed CAR-T cells." (PMID 41425090, 2025). "With the approval of the antibody-drug conjugate enfortumab vedotin (EV), NECTIN4 has emerged as a bona fide therapeutic target in urothelial carcinoma (UC)." (PMID 40931013, 2025).
urothelial carcinoma (continued). "Enfortumab vedotin (EV) is an antibody-drug conjugate targeting Nectin-4, which is highly expressed in urothelial carcinoma." (PMID 41021053, 2025). "A Nectin-4-targeted ADC (enfortumab vedotin) has already been approved for unresectable urothelial carcinoma that has progressed after chemotherapy." (PMID 40717183, 2025). "Enfortumab vedotin (EV) is an antibody-drug conjugate (ADC) targeting Nectin-4 that has revolutionized the treatment landscape of advanced urothelial carcinoma." (PMID 40496844, 2025). "Both studies also found relatively high Nectin‐4 expression rates in Sq urothelial carcinoma, with rates of 80% (8/10) and 70% (7/10)." (PMID 39801278, 2025). "In terms of urothelial carcinoma, HT-1376 has the highest nectin-4 expression followed by SW780, whereas UM-UC-3 has the lowest expression." (PMID 40774696, 2025). "In 2019, the Food and Drug Administration approved enfortumab vedotin, the first antibody–drug conjugate targeting Nectin-4, for the treatment of urothelial carcinoma." (PMID 38606099, 2024). "Enfortumab vedotine, which targets the cell adhesion molecule Nectin-4, was approved for the treatment of advanced urothelial carcinoma." (PMID 38539508, 2024). "The successful preclinical trials of Padcev for treating urothelial carcinoma have demonstrated the efficacy of targeting Nectin-4 in cancer drug development, concurrently propelling the advancement of Nectin-4 ADCs." (PMID 38755613, 2024). "detected the expression of Nectin-4 in 169 patients with urothelial carcinoma by immunohistochemistry." (PMID 38606099, 2024). "It targets Nectin-4, a protein found on urothelial carcinoma cells, allowing for the targeted delivery of the cytotoxic agent." (PMID 38668075, 2024). "The therapeutic efficacy of EV in patients with urothelial carcinoma has shown variations based on the histological and molecular characteristics of the tumors, particularly expression levels of Nectin-4." (PMID 38606099, 2024). "In 2019, the Food and Drug Administration (FDA) approved the first antibody-drug conjugate (ADC) targeting Nectin-4, known as enfortumab vedotin (EV), for treating urothelial carcinoma." (PMID 38606099, 2024). "Currently, Enfortumab vedotin—a monoclonal antibody–drug conjugate targeting nectin-4—is used as another tool for treatment of urothelial carcinoma." (PMID 37568798, 2023). "High expression of NECTIN4 or GATA3 in de novo NEPC regions is characteristic of urothelial carcinoma." (PMID 37240308, 2023). "Nectin-4 is a protein that is overexpressed in urothelial carcinoma cells, making it an ideal target for therapy." (PMID 37686503, 2023). "Urothelial carcinoma is one of the best-studied cancers in terms of nectin-4, given the available treatments based on targeting nectin-4 in this malignancy." (PMID 37568798, 2023). "As head and neck cancer and urothelial carcinomas share morphological and molecular similarities, we aimed to evaluate Nectin-4 expression in head and neck squamous cell carcinoma (HNSCC)." (PMID 36268557, 2022). "Nectin-4 is expressed in 69% of solid tumors and overexpressed in more than 60% of bladder cancers (or urothelial carcinomas), making it an attractive target for urothelial carcinoma treatment." (PMID 36209184, 2022). "It has been demonstrated that the vast majority of advanced urothelial carcinomas overexpress NECTIN4 and that this protein has great potential as a therapeutic target for patients with advanced-stage urothelial carcinoma." (PMID 35484425, 2022). "A phase II trial of patients with urothelial carcinoma, which highly expresses NECTIN4, has been reported." (PMID 32824340, 2020). "Recent phase I and II trials demonstrated the efficacy of enfortumab vedotin (EV), which targets Nectin-4 in urothelial carcinoma patients who exhibit tumor progression after platinum chemotherapy and/or immune checkpoint inhibitors." (PMID 32751328, 2020).
urothelial carcinoma (continued). "Enfortumab vedotin is a novel antibody–drug conjugate targeting Nectin-4, which is highly expressed in urothelial carcinoma." (PMID 32751328, 2020). "This study evaluates whether positron emission tomography (PET) imaging targeting Nectin-4 can noninvasively quantify the real-time interaction of the ADC enfortumab vedotin (EV) with tumors in urothelial carcinoma." (PMID 41499516, 2026). "Enfortumab vedotin is a standard therapy for advanced urothelial carcinoma, but its efficacy may be limited by acquired resistance and spatial heterogeneity of Nectin‐4 expression." (PMID 41403786, 2026). "Nectin-4 is a cell adhesion molecule expressed in various epithelial malignancies including urothelial carcinoma, as well as in normal skin tissues, specifically in basal keratinocytes, sweat glands, and hair follicles, thus predisposing patients to cutaneous reactions." (PMID 40144398, 2025). "However, in the EV‐301 trial, the presence of Nectin‐4 expression was not set as an inclusion criterion, based on the assumption that nearly all advanced urothelial carcinoma exhibits high Nectin‐4 expression." (PMID 39801278, 2025). "Enfortumab vedotin (EV), a drug antibody complex directed against nectin-4 shown to be highly expressed in urothelial carcinoma (UC), was FDA approved in late 2023 as a combination therapy approach with Pembrolizumab for patients with locally advanced or metastatic BC." (PMID 40964450, 2024). "This study demonstrates the utility of Nectin-4-targeted positron emission tomography (PET) imaging using [68Ga]AJ647 as a non-invasive tool for real-time assessment of target engagement in enfortumab vedotin (EV) therapy for urothelial carcinoma (UC)." (PMID 39763905, 2024). "The expression of Nectin-4 in urothelial carcinoma tumors can vary significantly." (PMID 38606099, 2024). "Urothelial carcinoma patients with overexpressed nectin-4 had a significantly worse prognosis." (PMID 35795565, 2022). "Nectin-4-targeted ADC therapy was applied in urothelial carcinoma." (PMID 35795565, 2022). "Nectin-4 is an antigen highly expressed in urothelial carcinoma." (PMID 33808614, 2021). "Enfortumab vedotin, a monoclonal anti-Nectin-4 antibody conjugated to the microtubule-disrupting agent monomethyl auristatin E (MMAE), binds to cells that express Nectin-4, a cell adhesion molecule that is highly expressed in several solid tumors, including urothelial carcinomas." (PMID 34768978, 2021). "Novel therapies with demonstrated efficacy in advanced urothelial carcinoma such as immunotherapeutics and nectin‐4 targeting may, in the future represent a safer and more effective perioperative strategy." (PMID 33710797, 2021). "This may be explained by the high expression rates of Nectin-4 in urothelial carcinomas." (PMID 36268557, 2022). "EV is an antibody-drug conjugate with monoclonal antibody directed against nectin-4, expressed on urothelial cells, conjugated to the microtubule disruptor monomethyl auristatin E (MMAE) used in the treatment of advanced urothelial carcinoma." (PMID 41446684, 2026). "Enfortumab vedotin (Padcev®), an ADC targeting nectin cell adhesion molecule 4 (NECTIN4), gained FDA approval for metastatic or advanced urothelial carcinoma in 2021." (PMID 40577962, 2025). "In urothelial carcinoma, enfortumab vedotin is an ADC drug targeting Nectin-4, which has been approved for the treatment of refractory metastatic bladder cancer." (PMID 40843358, 2025). "Enfortumab vedotin is a nectin-4-directed antibody and microtubule inhibitor conjugate, FDA and EMA-approved for the palliative treatment of urothelial carcinoma." (PMID 40427091, 2025). "Nectin-4 has emerged as an attractive target for ADC therapy, and in 2019, the FDA approved the first ADC (EV) targeting Nectin-4 for the treatment of urothelial carcinoma." (PMID 38606099, 2024).
urothelial carcinoma (continued). "Examples of successful ADCs include those targeting nectin-4 in urothelial carcinoma and targeting trophoblast cell-surface antigen 2 (TROP-2) in breast cancer and urothelial carcinoma." (PMID 38893204, 2024). "Enfortumab vedotin, an antibody–drug conjugate binding to Nectin-4, recently gained FDA approval for third-line urothelial carcinoma." (PMID 37480387, 2023). "Enfortumab vedotin (EV), a nectin-4-directed antibody conjugated to monomethyl auristatin E (MMAE), has been approved for patients with advanced urothelial carcinoma (aUC) previously treated with platinum-based chemotherapy and immune inhibitors." (PMID 36691441, 2023). "Additionally, Nectin‐4 expression was significantly higher in MPUC and significantly lower in the SARC, Sq and Sc/NE histological subtypes compared to pure urothelial carcinoma NOS subtypes." (PMID 39801278, 2025). "Similarly, the other study found no positive Nectin‐4 expression in any of the Sc/NE (0/15) urothelial carcinomas." (PMID 39801278, 2025). "However, the prognostic significance of Nectin-4 expression has not been investigated in urothelial carcinoma, including UTUC, to date." (PMID 32751328, 2020).